Y_RNA (Y RNA )
Gene: Miscellaneous RNA gene on chromosome 9 (109,324,685 to 109,324,796, forward strand). Ensembl gene ENSG00000207329.
Homologues: Orthologues: chimpanzee Y_RNA (99% identical), macaque Y_RNA (95% identical). Paralogues in human: RNY1 (86% identical), Y_RNA (85% identical), RNY1P11 (84% identical), Y_RNA (84% identical), Y_RNA (83% identical), Y_RNA (82% identical), Y_RNA (81% identical), RNY1P8 (80% identical), Y_RNA (80% identical), RNY1P7 (79% identical), Y_RNA (79% identical), RNY1P10 (78% identical), and 93 more.